ZFP36L2 (ZFP36 like 2 zinc finger CCCH-type)
Diseases named in the same sentence as ZFP36L2 in open-access papers (continued):
Sharing a sentence is not in itself a finding about the gene and the disease.
glioma (1 paper, 2022). A benign or malignant brain and spinal cord tumor that arises from glial cells (astrocytes, oligodendrocytes, ependymal cells). "Furtherly, increased levels of ZFP36L2 were detected by western blot in a more malignant glioma cell line, U87, indicating ZFP36L2 might be associated with glioma development at least in part." (PMID 35910229, 2022). "Considering the strong prognostic value of ZFP36L2 overexpression, we further explored the mechanism of ZFP36L2 upregulation in glioma." (PMID 35910229, 2022). "In current study, we used integrated bioinformatic approaches to explore the potential mechanisms of ZFP36L2 involvement in glioma development and its potential as a prognostic biomarker for LGG." (PMID 35910229, 2022). "In view of the significant association between ZFP36L2 overexpression and the development of glioma, we further explored the mechanism of ZFP36L2 upregulation in glioma." (PMID 35910229, 2022). "Thus, we will continue to explore the mechanism of ZFP36L2 involved in glioma development in a future study." (PMID 35910229, 2022). "The results showed that ZFP36L2 was significantly positively correlated with the three immune scores and multiple types of immune cells, while immune cells had been demonstrated being significantly related to the progression of glioma in previous studies." (PMID 35910229, 2022). "However, the clinical significance and prognostic value of ZFP36L2 in lower-grade glioma (LGG) remain unclear." (PMID 35910229, 2022). "This suggests that genetic changes may not be the main cause of ZFP36L2 upregulation in gliomas." (PMID 35910229, 2022). "But until now, the precise function and prognostic value of ZFP36L2 in lower-grade gliomas have not been elucidated." (PMID 35910229, 2022).
heart failure (1 paper, 2022). Inability of the heart to pump blood at an adequate rate to meet tissue metabolic requirements. "Finally, gross and histological examination of the hearts of pregnant mice with Zfp36l2 deletion treated with rapamycin displayed reduced size, heart weight/tibial length, and markers of heart failure (Anf and Bnp) compared with mice given vehicle control." (PMID 35316214, 2022). "Additionally, mRNA of markers of heart failure, Anf and Bnp, were increased in the hearts of Zfp36l2-KO mice after pregnancy; however, there was no significant change in overall cardiac histologic structure or degree of fibrosis." (PMID 35316214, 2022). "However, this pathway plays a specific role in pregnancy because deletion of Zfp36l2 does not exacerbate heart failure induced by TAC in mice." (PMID 35316214, 2022).
hepatic disorders (1 paper, 2025). "Finally, several miRNAs are involved in ZFP36L1 and ZFP36L2 regulations and are deregulated in hepatic disorders (e.g., mir-96 or miR-124-3p for ZFP36L1; miR-409-3p, miR-375 or miR-429 for ZFP36L2)." (PMID 39941720, 2025).
metastatic tumours (1 paper, 2021). "Specifically, ZFP36L2 was indicated as a tumour suppressor through pan-cancer whole-genome sequencing techniques highlighting ZFP36L2 to be significantly mutated in metastatic tumours." (PMID 35008519, 2021).
osteosarcoma (1 paper, 2024). A usually aggressive malignant bone-forming mesenchymal neoplasm, predominantly affecting adolescents and young adults. "Single-cell data analysis and cell–cell communication analysis were used to discover the therapeutic potential of ZFP36L2 in osteosarcoma." (PMID 39767767, 2024). "Cell–cell communication analysis indicates that ZFP36L2 targets TNF in IL1β+ osteosarcoma, thereby improving prognosis." (PMID 39767767, 2024). "A Kaplan–Meier survival curve was used to study the relationship between ZFP36L2 and IL1β in osteosarcoma." (PMID 39767767, 2024). "The survival analysis results show that ZFP36L2 can serve as a biomarker in IL1β+ osteosarcoma." (PMID 39767767, 2024).
peritonitis (1 paper, 2021). Inflammation of the peritoneum (tissue that lines the abdominal wall and covers most of the organs in the abdomen). "Mmp9, Rgs2 and Zfp36l2 were downregulated in both IL-1β-induced conditions, while Lyz2 and Lst1 were downregulated in IL-1β-induced pneumonitis but not peritonitis." (PMID 34001893, 2021).
polycystic ovarian syndrome (1 paper, 2022). "However, in humans, Zfp36l2 seems to be relevant after puberty as it is involved in polycystic ovarian syndrome." (PMID 35380695, 2022).
sarcoma (1 paper, 2024). A usually aggressive malignant neoplasm of the soft tissue or bone. "Given the substantial correlation of ZFP36L2 with metastasis rates in patients with sarcoma and the GSEA results, our investigation extended to the tumor immune microenvironment." (PMID 39767767, 2024). "Further investigation within the subgroup of OS in sarcoma unveiled a relationship between ZFP36L2 and IL1β, suggesting its potential as a prognostic marker and highlighting the heterogeneity of sarcomas." (PMID 39767767, 2024). "This study highlights the high expression levels of ZFP36L2 in patients with sarcoma and its low expression levels during metastasis." (PMID 39767767, 2024). "Subsequently, through TCGA database analysis using the Wilcoxon rank-sum test, we established a significant correlation between ZFP36L2 levels and sarcoma metastasis [p < 0.05]." (PMID 39767767, 2024). "High levels of ZFP36L2 expression promote cell proliferation in sarcomas." (PMID 39767767, 2024). "This study is based on our finding that ZFP36L2 overexpression is observed in sarcoma patients." (PMID 39767767, 2024). "Additionally, the CIBERSORT analysis demonstrated the strong association of high ZFP36L2 expression with macrophages and CD4+ T cells, particularly in sarcomas." (PMID 39767767, 2024). "Therefore, we screened ZFP36L2 and the signature cytokines secreted by M1 macrophages and conducted a Kaplan–Meier survival analysis using the OS database [OS is the most malignant sarcoma]." (PMID 39767767, 2024).
skin tumor (1 paper, 2021). "It would therefore be important to define the mechanisms leading to decreased ZFP36, ZFP36L1, and ZFP36L2 expression during skin tumor progression." (PMID 33497366, 2021).
squamous cell carcinoma (1 paper, 2019). A carcinoma arising from squamous epithelial cells. "Notably, the SV and ZFP36L2 expression and function differ between adenocarcinoma and squamous-cell carcinoma." (PMID 31048690, 2019).
Stroke (1 paper, 2024). Sudden impairment of blood flow to a part of the brain due to occlusion or rupture of an artery to the brain. "The results showed that 6 genes filtered with optimal lambda value were identified as diagnostic characteristic genes in stroke, namely, HAS3, VIM, ZFP36L2, CPQ, F5, and PIK3CG." (PMID 38649659, 2024). "After taking the intersection of SCFA metabolism-related genes and the co-expression WGCNA modules of stroke, 10 SCFA-related hub genes were obtained, and 6 of them showed high diagnostic efficacy through LASSO regression and ROC analysis, including HAS3, VIM, ZFP36L2, CPQ, F5, and PIK3CG." (PMID 38649659, 2024).
thyroid (1 paper, 2021). "Finally, apoptosis is an early and pivotal step in thyroid carcinogenesis, and ZFP36L2 inactivation results in its increase." (PMID 34502288, 2021).
tumor (22 papers, 2014 to 2025). "ZFP36L2 has been shown to be associated with T cells and macrophages in the tumor microenvironment through GO/KEGG analysis and immune infiltration analysis." (PMID 39767767, 2024). "Since a substantial fraction of mutations were frameshifts, the detected mutations and SVs were considered to impair the function of ZFP36L2 in most cases, suggesting ZFP36L2 as a tumor suppressor in CRC." (PMID 35343095, 2022). "Since it appeared that mutations in ZFP36L2 were enriched among rCRCs compared with among nrCRCs, we performed a survival analysis to explore the possibility that mutations in ZFP36L2 were associated with tumor recurrence." (PMID 35343095, 2022). "ZFP36L2 has been reported to be associated with tumour invasion." (PMID 34632655, 2021). "Therefore, ZFP36L2 could be a tumor suppressor for CRC, and its deficiency may predict recurrence or worse outcomes." (PMID 35343095, 2022). "Our analysis revealed variations in ZFP36L2 expression by comparing normal tissue samples with corresponding tumor samples, and different tumor types exhibited distinct expression patterns." (PMID 39767767, 2024). "ZFP36L2 is an anti-inflammatory protein that regulates posttranscription mRNA decay, playing a critical role in microenvironment immune interactions and tumor cell proliferation." (PMID 39767767, 2024). "The simultaneous expression of ZFP36L2 and IL1β in IL1β+ macrophages suggests a pivotal role of macrophages in the production of cytotoxic effects against tumor cells and the enhancement of prognosis." (PMID 39767767, 2024). "ESTIMATE algorithm and TIMER database were utilized to evaluate the correlation between ZFP36L2 expression and immune infiltration level in the tumor microenvironment of LGG samples." (PMID 35910229, 2022). "It was also reported that LOF of ZFP36L2 promotes tumor progression by impairing apoptosis due to DNA damage." (PMID 35343095, 2022). "Collectively, our study suggests that ZFP36L2 plays an important role in the tumor immune microenvironment and is predictive of immunotherapeutic response." (PMID 35910229, 2022). "Considering the strong correlation between ZFP36L2 expression and immune response and tumor microenvironment, we further evaluated its relationship with immunotherapy response." (PMID 35910229, 2022). "Given the sharp contrast of ZFP36L2 expression between tumor and normal tissues, we further evaluated the prognostic role of ZFP36L2 in LGG based on two independent cohorts, the TCGA and CGGA databases." (PMID 35910229, 2022). "Given that ZFP36L2 is involved in multiple immune-related pathways, we further evaluated its role in the tumor immune microenvironment." (PMID 35910229, 2022). "We initially evaluated ZFP36L2 mRNA expression levels in different human tumor and normal tissues based on TCGA TARGET GTEx cohort." (PMID 35910229, 2022). "In tumor number 1019, a deletion was found in the second exon of ZFP36L2 that resulted in truncation, whereas in tumor number 1031, we detected a deletion encompassing the entire region of ZFP36L2 and another in the promoter." (PMID 35343095, 2022). "GSEA analysis shown that several immune and tumor-related terms were enriched in ZFP36L2-high expression cohort, including epithelial mesenchymal transition, interferon alpha response and interferon gamma response." (PMID 35910229, 2022). "Like ZFP36L1, ZFP36L2 has also been indicated to play oncogenic and tumour suppressive roles in different cancer types." (PMID 35008519, 2021). "More recently, we demonstrated the anti-tumour roles of miR-375 through its targeting of ZFP36L2 in PDAC cells." (PMID 29050264, 2017). "By comparing the DMRs in the differentiated and poorly differentiated tumor regions, loss of imprinting around the ZFP36L2 gene was observed, although its expression level was not much different among the regions." (PMID 41187747, 2025).
tumor (continued). "In addition, ZFP36L2 is highly correlated with tumor progression, particularly in acute myelocytic leukemia, lower-grade gliomas, and gastric cancer." (PMID 39767767, 2024). "Given the tumor-specific expression patterns of ZFP36L2 across various cancer types, we hypothesized that these differences are linked to variations in the TME, which in turn is intricately tied to the immune response." (PMID 39767767, 2024). "Given that ZFP36L2 is a posttranscriptional regulator, we hypothesized that it plays an important role in tumor progression and is a potential biomarker." (PMID 39767767, 2024). "In addition, ZFP36L2 mediates multiple immune response pathways and is involved in the regulation of the tumor microenvironment." (PMID 35910229, 2022). "Similar to TTP and ZFP36L1, ZFP36L2 also functions as a tumor suppressor." (PMID 32545247, 2020). "PROCA1 played a potential tumor-suppressive role inducing cell apoptosis and DDP chemosensitivity via recruiting ZFP36L2 to bind to the 3′ untranslated region of BCL2, reducing the stability of BCL2 mRNA and thus activating the apoptotic signal." (PMID 36627670, 2023). "Consequently, the decreased expression of ZFP36L2 leads to the increased secretion of cytokines, such as IL1β, MMP-9, and TNF-α, by T cells, thereby promoting tumor apoptosis." (PMID 39767767, 2024). "ZFP36L2, a member of the tristetraprolin family of CCCH zinc finger proteins, stands out for its pivotal role in posttranscriptional modifications and its ability to modify tumor microenvironments." (PMID 39767767, 2024).
cancer (19 papers, 2014 to 2024). A tumor composed of atypical neoplastic, often pleomorphic cells that invade other tissues. "For example, H1FX has mainly been highlighted to be associated with cancer to date, whereas ZFP36L2 was reported to induce apoptosis and inhibit cell proliferation." (PMID 36916943, 2023). "To investigate the differential expression of ZFP36L2 across various cancer types, we utilized the TCGA database." (PMID 39767767, 2024). "ZFP36L2 demonstrates notable heterogeneity across various cell components in different types of cancer, including OS." (PMID 39767767, 2024). "TTP and its paralogues ZFP36L1 and ZFP36L2 have significant roles in cancer and regulation of the immune system through binding and repressing the expression of mRNAs that contain A/U rich elements." (PMID 37732428, 2023). "ZFP36L2 belongs to the zinc finger protein family and plays an opposite role in different types of cancer." (PMID 35910229, 2022). "The two specific luminal B candidates, ASS1 and ZFP36L2 downregulated in relation with DNA methylation have been reported targeted in cancers." (PMID 24416132, 2014). "Nevertheless, each scenario underscores the importance of ZFP36L2 in cancer progression." (PMID 39767767, 2024). "ZFP36L2 is responsible for an increase in cancer cell aggressiveness." (PMID 33854844, 2021). "Finally, in the pan-cancer database, we detected SRGAP3 and ZFP36L2 as putative cancer-related genes." (PMID 26429873, 2015). "Genes such FAM182A, SOX9, AHNAK2, ENSG00000121031, FLT3LG, PMEPA1, ZFP36L2 in the large intestine, ALB, KRTAP19-1, APOB, CD200, CRYGD, KRTAP24-1, OR6N2 in the liver are novel predictions, and their functions in these cancers can further be studied." (PMID 34997044, 2022). "Novel candidate cancer genes include ZFP36L1 and ZFP36L2, which have recently been shown to promote cellular quiescence and suppress S-phase transition during B cell development." (PMID 29056346, 2017). "Knockout of ZFP36L2 with CRIPSR/Cas 9 facilitates the metastatic potential of CRC cells, illuminating ZFP36L2 may act as a suppressor in cancer progression." (PMID 34632655, 2021).
infection (14 papers, 2013 to 2025). The state of being infected such as from the introduction of a foreign agent such as serum, vaccine, antigenic substance or organism. "We optimized adeno-Cre multiplicity of infection (MOI) based on loss of Zfp36, Zfp36l1, and Zfp36l2 mRNA expression and confirmed loss of ZFP36 and ZFP36L1 protein expression in the adeno-Cre-infected, FBS-stimulated Zfp36/l1/l2 triple-floxed MEFs." (PMID 37086408, 2023). "Cells overexpressing ZFP36L1, ZFP36L2, or EGFP were infected with JEV and DENV at a high MOI, and the viral load and protein expression levels were measured at 24 h post-infection (hpi)." (PMID 39972499, 2025). "These analyses showed that depletion of DOHH, PRKRA, SEL1L, UBE2G2, and ZFP36L2 consistently decreased DENV-2 viral protein and RNA levels during infection of Huh7.5.1 cells (respectively)." (PMID 41372121, 2025). "In this study, we examined the distribution of ZFP36L2, XRN1, and viral dsRNA during infection, with confocal imaging revealing their colocalization within the RCs." (PMID 39972499, 2025). "Consequently, the levels of endogenous ZFP36L2 were predominantly upregulated in JEV- and DENV-infected cells, particularly during the late stages of the infection." (PMID 39972499, 2025). "All three ZFP36-family paralogues can be expressed by T cells, and, in the absence of infection or inflammation, ZFP36L1 is the most abundant in Treg cells and exerts non-redundant essential functions that are compensated partially by ZFP36L2." (PMID 40328742, 2025).
hematological disease (3 papers, 2016 to 2022). "Compared to T-ALL or B-ALL, super-enhancers associated with MPO were observed to be AML specific, while super-enhancers associated with ZFP36L2 were common to all three hematological diseases (AML, T-ALL, and B-ALL)." (PMID 35842703, 2022). "The inhibition of Egr1, Hmga1 and Zfp36l2 transcripts was also related to hematological disease by IPA analysis, especially defects in erythropoiesis in CPF and ETU." (PMID 27905518, 2016).
female reproductive disease (1 paper, 2014). "This novel biological role for the ZFP36L2 protein in ovulation and oocyte maturation suggests a relevant function for ZFP36L2 in female reproductive disease." (PMID 24830504, 2014).
ZFP36L2 also shares sentences with these, for which no sentence is quoted: cervical cancer (2 papers); ovarian carcinoma (2); Pancytopenia (2); adenocarcinoma (1); adult T-cell leukemia/lymphoma (1); Cognitive impairment (1); colorectal adenoma (1); esophageal cancer (1); glaucoma (1); Insulin resistance (1); lung carcinoma (1); melanoma (1); myocardial ischemia (1); non-small cell lung carcinoma (1); peripartum cardiomyopathy (1); pneumonitis (1); prostatic neoplasms (1); sitosterolemia (1); steatosis (1); systemic lupus erythematosus (1); thyroid cancer (1); viral infections (1); Wilms tumor (1).